HOMER3 (homer scaffold protein 3)
Description:
Postsynaptic density scaffolding protein. Binds and cross-links cytoplasmic regions of GRM1, GRM5, ITPR1, DNM3, RYR1, RYR2, SHANK1 and SHANK3. By physically linking GRM1 and GRM5 with ER-associated ITPR1 receptors, it aids the coupling of surface receptors to intracellular calcium release. Isoforms can be differently regulated and may play an important role in maintaining the plasticity at glutamatergic synapses. Negatively regulates T cell activation by inhibiting the calcineurin-NFAT pathway. Acts by competing with calcineurin/PPP3CA for NFAT protein binding, hence preventing NFAT activation by PPP3CA.
Synonyms: Homer-3; VESL3
Tractability: Small molecule: it has a binding pocket of medium quality. Antibody: its Gene Ontology location is reachable by antibodies, with medium confidence; the Human Protein Atlas places it where antibodies can reach. PROTAC: ubiquitination databases record sites on it; its protein half-life has been measured.
Gene: Protein-coding gene on chromosome 19 (18,929,201 to 18,941,728, reverse strand). Ensembl gene ENSG00000051128.
Subcellular location: Cytoplasm; Postsynaptic density; Synapse
Subcellular location (Human Protein Atlas): Cytosol; Cytoplasmic bodies; Plasma membrane
Pathways (Reactome):
Neuronal System: Neurexins and neuroligins
Gene Ontology:
Molecular function: identical protein binding; protein binding; G protein-coupled glutamate receptor binding
Biological process: negative regulation of calcineurin-NFAT signaling cascade; negative regulation of interleukin-2 production; G protein-coupled glutamate receptor signaling pathway; protein targeting; regulation of store-operated calcium entry; regulation of synaptic transmission, glutamatergic
Cellular component: cytosol; plasma membrane; cytoplasm; dendrite; postsynaptic density; synapse
Genetic constraint (gnomAD): Loss-of-function variants: 29 observed, 32.03 expected, observed/expected ratio (o/e) 0.91, 90% interval 0.67 to 1.24. The synonymous counts are far from expectation, so gnomAD's model fits this gene poorly and the ratio says little. Missense variants: 469 observed, 403.52 expected, observed/expected ratio (o/e) 1.16, 90% interval 1.08 to 1.25. Synonymous variants: 217 observed, 166.62 expected, observed/expected ratio (o/e) 1.3, 90% interval 1.16 to 1.46.
Homologues: Orthologues: macaque HOMER3 (99% identical), chimpanzee HOMER3 (98% identical), dog HOMER3 (94% identical), pig HOMER3 (94% identical), guinea pig HOMER3 (91% identical), mouse Homer3 (89% identical), rat Homer3 (78% identical), tropical clawed frog homer3 (64% identical), zebrafish homer3b (54% identical), zebrafish homer3a (24% identical). Paralogues in human: HOMER1 (51% identical), HOMER2 (44% identical).
Diseases named in the same sentence as HOMER3 in open-access papers:
HOMER3 is named in the same sentence as 34 diseases in open-access papers, as found by Europe PMC text mining. Sharing a sentence is not in itself a finding about the gene and the disease. The quoted sentences say what the papers report.
breast carcinoma (5 papers, 2020 to 2023). "The clinical significance of HOMER3 expression was further assessed in the 347 breast cancer specimens." (PMID 33407765, 2021). "Role of HOMER3 in breast cancer metastasis was determined by cell function assays and mice tumor models." (PMID 33407765, 2021). "HOMER3 expression was examined by immunohistochemistry in breast cancer patient specimens, and its significance in prognosis was assessed by Kaplan–Meier survival analysis." (PMID 33407765, 2021). "In summary, our study reveals that HOMER3 is a critical regulator in growth factor-induced β-Catenin activation and promotes metastasis in breast cancer." (PMID 33407765, 2021). "Significantly, IHC staining and subsequent correlation analysis revealed that HOMER3 positively correlated with nuclear β-Catenin in the cohort of 347 breast cancer patient specimens." (PMID 33407765, 2021). "Considering that HOMER3 is a scaffolding protein, we then performed a Gene set enrichment analysis (GSEA) of the TCGA breast cancer samples according to HOMER3 expression to identify its regulated oncogenic signals." (PMID 33407765, 2021). "Collectively, these results reveal that robust increase of HOMER3 may play an important role in the progression of breast cancer, especially in TNBC." (PMID 33407765, 2021). "Taken together, our findings suggest that HOMER3 provides a scaffold platform to promote Tyr phosphorylation and activation of β-Catenin, leading to the malignant progression and poor clinical outcomes in human breast cancer." (PMID 33407765, 2021). "Furthermore, we used in vivo tumor models to assess the potential of targeting HOMER3 in breast cancer metastasis suppression." (PMID 33407765, 2021). "Finally, we evaluated the clinical relevance and significance of HOMER3/β-Catenin axis in breast cancer." (PMID 33407765, 2021). "We further investigated the role of HOMER3 in the aggressiveness of breast cancer cells." (PMID 33407765, 2021). "Understanding the precise role of HOMER3 in breast cancer pathogenesis and in the assembly of c-Src/β-Catenin complex promises to increase our knowledge of the biological basis of TNBC malignant progression and may also facilitate the development of new therapeutic strategies against TNBC." (PMID 33407765, 2021). "Importantly, breast cancer patients with high HOMER3 expression significantly suffered earlier metastasis and shorter survival time, and this high HOMER3 expression signature could be recognized as one of the independent prognostic factors for the prognosis of tumor metastasis and patient survival." (PMID 33407765, 2021). "HOMER3 belongs to the HOMER family of density scaffolding proteins and was revealed to promote breast cancer progression via activating Wnt/β-catenin signaling." (PMID 34815380, 2021). "Importantly, Kaplan–Meier survival curves and log-rank tests revealed that patients with combined high HOMER3 expression and positive nuclear β-Catenin expression suffered poorest 5-year DMFS and OS in breast cancer patients." (PMID 33407765, 2021). "However, no significant copy number alteration of the HOMER3 genomic locus could be observed from the TCGA breast cancer dataset." (PMID 33407765, 2021).
glioma (5 papers, 2018 to 2023). A benign or malignant brain and spinal cord tumor that arises from glial cells (astrocytes, oligodendrocytes, ependymal cells). "This provides further evidence that Homer3, as a dendritic protein, potentially contributes to worsening glioma by affecting the glycolysis system." (PMID 29497031, 2018). "We also revealed how WBP2 promotes cell proliferation and regulates the cell cycle by modulating ENO1 activity and the ENO1-PI3K/Akt signaling pathway by binding to ENO1 and Homer3 in glioma cells." (PMID 29497031, 2018). "Homer3 has been shown to directly interact with WW domain-binding protein 2 (WBP2) in glioma cells." (PMID 32070057, 2020). "Our data indicated that ENO1 and Homer3 had high coverage rates with WBP2, and previous studies have confirmed that both ENO1 and Homer3 are associated with glioma and nervous system development, suggesting these two proteins are an integral part in WBP2-mediated glioma cell growth and metastasis." (PMID 29497031, 2018). "We screened two potential partner proteins, ENO1 and Homer3, that showed high coverage with WBP2; their corresponding genes are vital in the development of glioma and the nervous system, respectively." (PMID 29497031, 2018). "In addition, Homer protein 3 (HOMER3), a member of HOMER, together with WW domain binding protein 2 (WBP2) plays a significant role in glioma invasion." (PMID 33969375, 2021). "Therefore, our data confirm that interactions between ENO1, Homer3, and WBP2 potentially mediate the cancer-promoting effects initiated by upregulation of WBP2 in glioma cells." (PMID 29497031, 2018). "However, the cross-talk between ENO1, Homer3, and WBP2 remains poorly understood in the progression of glioma." (PMID 29497031, 2018).
bladder cancer (3 papers, 2021 to 2023). "On the other hand, HOMER3 is a poorly studied protein in cancer, being herein reported for the first time in bladder cancer and, so far, nothing was yet known about its contribution to disease and biomarker potential." (PMID 34108014, 2021). "Upon microenvironmental challenges, HOMER3 supported invasion, most likely endowing cells with escape mechanisms, suggesting bladder cancer cells adaptive responses." (PMID 34108014, 2021). "Plasma membrane homer scaffold protein 3 (HOMER3) is often highly expressed in more aggressive primary tumors and distant metastases, and has been reported to be an independent predictor of worst prognosis in bladder cancer." (PMID 38081871, 2023). "Recently, through the application of glycoproteomics in bladder cancer, the same group demonstrated cell surface expression of an ordinarily intracellular protein, homer homolog 3 (HOMER3), carrying short-chain O-glycans that are characteristic of membrane proteins." (PMID 35211123, 2022). "Interestingly, HOMER3 is an intracellular protein with a restricted expression pattern in healthy tissues; however, in bladder cancer it was found at the cell surface carrying sialylated short-chain O-glycans, which are typically extracellular glycans." (PMID 34108014, 2021). "Notably, the expression of HOMER3 at the cell membrane in patients with MIBC, which generally present worst prognosis, was also associated with decreased OS in bladder cancer (mean: 15 vs 64 month; log-rank p = 0.001)." (PMID 34108014, 2021). "Furthermore, HOMER3 has been identified as an independent predictor of poor prognosis in bladder cancer." (PMID 34108014, 2021).
triple-negative breast carcinoma (3 papers, 2021 to 2024). An invasive breast carcinoma which is negative for expression of estrogen receptor (ER), progesterone receptor (PR), and human epidermal growth factor receptor 2 (HER2). "Herein, we find that, among the three HOMER proteins, HOMER3 is selectively overexpressed in the most aggressive triple negative breast cancer (TNBC) subtype, and significantly correlates with earlier tumor metastasis and shorter patient survival." (PMID 33407765, 2021).
cerebellar ataxia (2 papers, 2021 to 2022). A neurological syndrome characterized by clumsy and uncoordinated movement of the limbs, trunk, and cranial muscles. "Autoimmune aetiologies include 2 cases of ataxia secondary to Homer‐3 antibodies and a delayed appearance of the HCBS by 24 months." (PMID 36339304, 2022).
depression (2 papers, 2023). "Nevertheless, a whole-exome sequencing study of 184 samples with major depressive disorder discovered five cases carrying rare missense variants of HOMER3, suggesting that rare genetic variants of HOMER3 might be associated with major depressive disorder." (PMID 37511534, 2023). "Instead, we saw three rare variants that might be relevant to major depressive disorder, including p.Ala4551Gly of FAT1, p.Val231Leu of HOMER3, and p.Ile185Met of GPM6B." (PMID 37511534, 2023). "In family 2, with two affected sisters diagnosed with major depressive disorder, we detected three rare variants shared by the two sisters in three genes implicated in affective disorders, including p.Ala4551Gly of FAT1, p.Val231Leu of HOMER3, and p.Ile185Met of GPM6B." (PMID 37511534, 2023).
lung carcinoma (2 papers, 2023 to 2024). "Lung cancer cells with low levels of HOMER3 are found to show significant mitochondrial dysfunction, thereby suppressing their proliferation and metastasis in vivo and in vitro." (PMID 38081871, 2023). "To determine the role of HOMER3 in lung cancer metastasis, we performed scratch assay, cell migration assay and cell invasion assay in A549 and H1299 cells." (PMID 38081871, 2023). "In another experiment, luciferase-labeled H1299 cells were injected in to Balb/c nude mice to exam the effect of HOMER3 knockdown on lung cancer metastasis in vivo." (PMID 38081871, 2023). "The results indicated that HOMER3 knockdown significantly inhibited the proliferation of lung cancer cells." (PMID 38081871, 2023). "Low levels of HOMER3 or GABPB1 cause severe mitochondrial dysfunction, thereby inhibiting the growth and metastasis of lung cancer." (PMID 38081871, 2023). "Our study revealed that the knockdown of HOMER3 led to marked mitochondrial dysfunction in lung cancer cells." (PMID 38081871, 2023). "In conclusion, this study demonstrated the remarkable efficacy of HOMER3 in regulating the metabolism, proliferation, and metastasis of lung cancer cells." (PMID 38081871, 2023). "Knockdown of HOMER3, significantly decreased the proliferation and invasion abilities of lung cancer cells in vitro and in vivo." (PMID 38081871, 2023). "Moreover, overexpression of GABPB1 also partially reversed the decrease of invasive ability and lung metastasis of lung cancer cells induced by HOMER3 knockdown." (PMID 38081871, 2023). "Therefore, we believe that HOMER3 controls the tumorigenic potential of lung cancer by regulating the GABPB1-dependent mitochondrial Asp synthesis." (PMID 38081871, 2023). "Mechanistically, the binding of HOMER3 and PAFAH1B3 activates the transcriptional regulation of mitochondrial genes by GABPB1 in lung cancer cells." (PMID 38081871, 2023). "Therefore, to determine whether HOMER3 regulates the proliferation, apoptosis and invasion of lung cancer cells by binding to other proteins, and to identify HOMER3-binding proteins, we performed Co-IP followed with LC-MS/MS in H1299 cells with overexpressing HOMER3 and control cells." (PMID 38081871, 2023).
bladder tumours (1 paper, 2021). "Namely, HOMER3 was found carrying the cancer associated STn antigen, which is rarely observed in healthy organs and significantly overexpressed by more aggressive bladder tumours and, particularly, hypoxic cells." (PMID 34108014, 2021). "We concluded that more aggressive bladder tumours and its metastases exuberantly expressed HOMER3 at the cell surface modified with sialylated short-chain O-glycans typical of membrane proteins." (PMID 34108014, 2021). "Finally, we have observed that HOMER3 in bladder tumours is glycosylated with simple sialylated O-glycoforms, in agreement with observations from cell models." (PMID 34108014, 2021).
Cirrhosis (1 paper, 2021). A chronic disorder of the liver in which liver tissue becomes scarred and is partially replaced by regenerative nodules and fibrotic tissue resulting in loss of liver function. "For Homer3, its expression in HCC was lower than that in cirrhosis (P < 0.01), hepatitis B (P < 0.01) and the controls (P < 0.01) and Homer3 expression in cirrhosis (P < 0.05) and hepatitis B (P < 0.01) were lower than that in controls." (PMID 33995622, 2021). "We tested the expression of Homer2 and Homer3 in peripheral blood in 72 HCC patients, 59 cirrhosis patients, 52 hepatitis B, and 109 control cases." (PMID 33995622, 2021).
diabetes (1 paper, 2014). "The gene expression of Homer1, Homer2, Homer3, IL-1β, and TNF-α were analyzed by hypertension and diabetes between CAD patients and controls." (PMID 25551602, 2014). "Subgroup analyses of the gene expression of Homer1, Homer2, Homer3, IL-1β, and TNF-α between CAD patients and controls by hypertension and diabetes." (PMID 25551602, 2014).
esophageal squamous cell carcinoma (1 paper, 2021). Esophageal squamous cell carcinoma (ESCC) is a type of esophageal carcinoma (EC) that can affect any part of the esophagus, but is usually located in the upper or middle third. "Notably, a recent report indicates that genomic amplification contributes to HOMER3 overexpression in esophageal squamous cell carcinoma." (PMID 33407765, 2021).
hepatocellular carcinoma (1 paper, 2023). A malignant tumor that arises from hepatocytes. "The HOMER3 antisense RNA 1 (HOMER3-AS1) induced by Wnt/β-catenin upregulates HOMER3 and promotes M2 TAM polarization in hepatocellular carcinoma." (PMID 36831498, 2023).
leukemia (1 paper, 2021). A malignant (clonal) hematologic disorder, involving hematopoietic stem cells and characterized by the presence of primitive or atypical myeloid or lymphoid cells in the bone marrow and the blood. "For instance, in leukemia, HOMER3 inhibits expression of Bcl2 thus influencing the cell cycle." (PMID 33969375, 2021).
lymph node metastasis (1 paper, 2021). "Correlation analysis showed that high levels of HOMER3 were significantly associated with advanced clinical stage, lymph node metastasis, tumor size, as well as 5-year distant metastasis status and patient vital status." (PMID 33407765, 2021).
Tinnitus (1 paper, 2021). Tinnitus is an auditory perception that can be described as the experience of sound, in the ear or in the head, in the absence of external acoustic stimulation. "We found that Homer1 expression was upregulated in the auditory cortex of mice with tinnitus, while expression of Homer2 or Homer3 exhibited no significant alteration." (PMID 34546852, 2021). "After establishing a salicylate-stimulated tinnitus mouse model, expression of Homer genes in the auditory cortex was detected and we identified upregulated expression of Homer1, but not of Homer2 or Homer3 in auditory cortex of mice after salicylate stimulation." (PMID 34546852, 2021).